DAXX (death domain associated protein)
Diseases named in the same sentence as DAXX in open-access papers (continued):
Sharing a sentence is not in itself a finding about the gene and the disease.
leiomyosarcoma (4 papers, 2021 to 2025). An uncommon, aggressive malignant smooth muscle neoplasm, usually occurring in post-menopausal women. "In leiomyosarcoma patients, loss of ATRX or DAXX expression was associated with lower DFS and lower OS, while only one case of cellular uterine leiomyoma (UL) exhibited the loss of DAXX expression." (PMID 37958340, 2023). "Likewise, the hypermethylation of ZNF433 has been related to the progression of clear cell renal cell carcinoma and the differential methylation and overexpression of DAXX in the progression of leiomyosarcoma." (PMID 39858027, 2025). "Since there is a correlation between ATRX/DAXX loss and an ALT+ phenotype in ULMS, these characteristics could potentially be used as markers to better discern STUMP entities as either uterine leiomyomas or leiomyosarcomas." (PMID 34069193, 2021).
oligodendroglioma (4 papers, 2016 to 2019). A well-differentiated (WHO grade II), diffusely infiltrating neuroglial tumor, typically located in the cerebral hemispheres. "Recently, it has been shown that many ALT-positive tumors, including PanNETs, oligodendrogliomas, and GBM, contain inactivating mutations in ATRX and/or DAXX, implicating the possible role of ATRX/DAXX inactivation in the manifestation of the ALT phenotype." (PMID 29359122, 2017).
pancreatic cancer (4 papers, 2017 to 2024). "DAXX has been proved to play an anti-tumor role in pancreatic cancer by inhibiting the expression of some genes, and improving the repeated sequence and repairing DNA in vivo." (PMID 39877345, 2024). "Furthermore, bioinformatics analysis showed high levels of DAXX expression in metastatic pancreatic cancer which correlates with decreased patient survival with low levels of expression in normal prostate glands." (PMID 28596481, 2017).
pancreatic neuroendocrine cancers (4 papers, 2020 to 2023).
bladder cancer (3 papers, 2025). "Male-specific hub genes, including DAXX, IKBKB, PDGFRA, and PPARG, showed significant correlations with immune cell types, highlighting a distinct immune microenvironment in male bladder cancer." (PMID 40458476, 2025). "In our cohort, DAXX and ATRX expression exhibited distinct patterns in prostate and urinary bladder cancers." (PMID 41472189, 2025). "In men, alterations in DAXX and/or ATRX expression were reported for both prostate and urinary bladder carcinomas." (PMID 41472189, 2025).
cervical carcinoma (3 papers, 2014 to 2025). A carcinoma arising from either the exocervical squamous epithelium or the endocervical glandular epithelium. "As is the case for gastric cancer, DAXX intracellular location seems to constitute a key factor regarding its tumorigenic role in cervical cancer." (PMID 37958340, 2023). "DAXX is eventually located in the cytoplasm and cell membrane in CIN2, CIN3, and cervical cancer cells." (PMID 37958340, 2023).
colorectal cancer (3 papers, 2015 to 2024). A primary or metastatic malignant neoplasm that affects the colon or rectum. "Its involvement in colorectal cancer initiation is attributed to the upregulation of death-domain-associated protein, establishing a positive feedback regulatory relationship that promotes colorectal cancer progression." (PMID 38213716, 2024). "This excess CENP-A partners with histone H3, and associates with transcriptionally coupled chaperones ATRX and DAXX in colorectal cancer cell lines." (PMID 25788983, 2015).
lymph node metastasis (3 papers, 2020 to 2022). "Furthermore, we found that DAXX expression in different locations was significantly associated with lymph node metastasis, Lauren type, CA72-4 and relapse (P < 0.01)." (PMID 32641734, 2020).
Uterine leiomyoma (3 papers, 2021 to 2023). The presence of a leiomyoma of the uterus. "In a cohort of variant uterine leiomyoma patient samples, 6% (9/142) showed ALT-relevant aberrations, such as ATRX/DAXX loss and/or ultra-bright telomeric foci." (PMID 34069193, 2021).
chondrosarcoma (2 papers, 2019 to 2023). A malignant cartilaginous matrix-producing mesenchymal neoplasm arising from the bone and soft tissue. "On the contrary, DAXX immunoexpression was observed as significantly higher in chondrosarcoma than in osteochondroma tissues, and positive DAXX expression positivity associated with shorter patients’ OS." (PMID 37958340, 2023). "Associations of DAXX, DRD3, and DISC1 expression with the clinicopathological characteristics of chondrosarcoma." (PMID 31850367, 2019). "Associations of DAXX, DRD3, and DISC1 expression and clinicopathological characteristics with overall survival in patients with chondrosarcoma, as determined by multivariable Cox regression." (PMID 31850367, 2019). "Therefore, DAXX role is designated as tumorigenic in a subset of sarcomas, namely chondrosarcomas, with a potential role as a biomarker of grim prognosis." (PMID 37958340, 2023). "In this study, the expression and clinicopathological significance of the mental health–related proteins DAXX, DRD3, and DISC1 in chondrosarcoma tissue samples were examined, over an 84-months follow-up period." (PMID 31850367, 2019). "In immunohistochemical analysis, the rates of positive DAXX, DRD3, and DISC1 expression were significantly higher in chondrosarcoma than in osteochondroma tissue (P < 0.01)." (PMID 31850367, 2019). "Relationships of DAXX, DRD3, and DISC1 expression and clinicopathological characteristics to average survival in patients with chondrosarcoma." (PMID 31850367, 2019). "In competing-risks regression analysis, differentiation (P = 0.005), metastasis (P = 0.014), invasion (P = 0.028), AJCC stage (P = 0.003), Enneking stage (P = 0.036), and DAXX (P = 0.039), and DRD3(P = 0.019) expression were independent predictors of death from chondrosarcoma." (PMID 31850367, 2019). "DAXX, DRD3, and DISC1 expression in chondrosarcoma and osteochondroma." (PMID 31850367, 2019).
HCMV infection (2 papers, 2009 to 2020). "Notably, this group contained the known HCMV restriction factors Sp100, MORC3, DAXX, and HLTF in addition to cell cycle regulating protein ANAPC1, all of which have been reported to be degraded during HCMV infection by ourselves and others." (PMID 33585265, 2020).
meningioma (2 papers, 2017). A generally slow growing tumor attached to the dura mater. "It is possible that other known cancer-specific mechanisms of telomere maintenance such as ATRX/DAXX mutations or TERT rearrangements could be present in meningiomas." (PMID 29312603, 2017). "Together with a recent report of no loss of ATRX or DAXX expression by IHC in 58 grade II and III meningiomas, these results provide evidence that the ALT pathway is not a frequent mechanism for telomere maintenance in progressive higher-grade meningiomas." (PMID 29312603, 2017).
ACTHomas (1 paper, 2020). "Additionally, whole exome sequencing (WES) analysis revealed several other mutations associated with ACTHomas, including those in the NR3C1, DAXX, ATRX, and HCFC1 genes." (PMID 33266265, 2020).
acute lymphoblastic leukemia (1 paper, 2019). Leukemia with an acute onset, characterized by the presence of lymphoblasts in the bone marrow and the peripheral blood.
acute myeloid leukemia (1 paper, 2013). Acute myeloid leukemia (AML) is a group of neoplasms arising from precursor cells committed to the myeloid cell-line differentiation. "Most DAXX and ATRX mutations are mutually exclusive and result in loss of expression, apart from a missense mutation found in acute myeloid leukemia (AML)." (PMID 23760585, 2013).
adenoma (1 paper, 2017). A neoplasm arising from the epithelium. "The same conclusion was recently reached also for sporadic PanNET: aberrant MEN1 expression was observed in 74% of micro-adenomas; in contrast, none of these micro-adenomas display the alternative lengthening of telomeres phenotype and do not display DAXX and ATRX loss." (PMID 29156578, 2017).
autoimmune disease (1 paper, 2022). A disorder resulting from loss of function or tissue destruction of an organ or multiple organs, arising from humoral or cellular immune responses of the individual to their own tissue constituents. "Moreover, DAXX is known to be an extended Class II, non-antigen binding HLA (human leukocyte antigen) gene associated with autoimmune diseases that interacts with death receptor Fas related to ASD." (PMID 35836289, 2022).
benign prostatic hyperplasia (1 paper, 2015). A non-cancerous nodular enlargement of the prostate gland. "Moreover, strong positive DAXX staining has been observed in PCa tissues, compared to benign prostatic hyperplasia (BPH) tissues, suggesting that DAXX is overexpressed in PCa." (PMID 26097870, 2015).
bladder tumours (1 paper, 2025). "Our findings provide a better understanding of how DAXX and ATRX expression is altered in canine prostate and bladder tumours, indicating that their potential clinical relevance should be further investigated." (PMID 41472189, 2025).
breast NETs (1 paper, 2022). "Likewise, MEN1 (6%) and DAXX (2%) had rarely pathogenetic or unknown variants in breast NETs, with pathogenetic or unknown variant rates of 37% and 22% in PNETs." (PMID 36085291, 2022). "Furthermore, typical pathogenetic or unknown variants of PNETs and other NENs, such as ATRX, DAXX and MEN1, were very rarely detected in breast NETs." (PMID 36085291, 2022).
Burkitt lymphoma (1 paper, 2023). A rare form of malignant mature B-cell non-Hodgkin lymphoma. "Our results showed that the mRNA and protein levels of DAXX were increased in CHAF1B-depleted cells; comparable results have been reported in Burkitt lymphoma cells." (PMID 37129573, 2023).
cystic neoplasm (1 paper, 2025). A benign or malignant neoplasm that contains a single or multiple cystic spaces. "However, the most common molecular alterations found in ductal adenocarcinoma (KRAS), cystic neoplasms (GNAS and RNF43), and NENs (MEN1, DAXX, and ATRX) are rarely found in ACC." (PMID 41120769, 2025).
dementia (1 paper, 2023). Loss of intellectual abilities interfering with an individual's social and occupational functions. "DAXX, a polyD/E protein, has recently been discovered to be an efficient molecular chaperone that inhibits aggregation, dissolves previously present aggregates, and unfolds misfolded kinds of model substances and proteins linked to dementia." (PMID 37553782, 2023).
diffuse large B-cell lymphoma (1 paper, 2024). "Moreover, in diffuse large B-cell lymphoma (DLBCL), an aggressive form of non-Hodgkin lymphoma, high levels of eIF4B increase the expression of key survival proteins, including BCL-2, DAXX and ERCC5, and are prognostic of poor patient outcome." (PMID 39225047, 2024).
hematoma (1 paper, 2023). A hematoma is a collection of blood from a vascular structure into an extravascular space. "Thus, DAXX may be a therapeutic target to increase hematoma absorption and provide insight into ICH treatment." (PMID 37553782, 2023).
hyperphosphatemia (1 paper, 2020). Abnormally high level of phosphate in the blood. "The rat model of CKD revealed that hyperphosphatemia is correlated with an increased death-domain associated protein (DAXX) expression in endothelial cells." (PMID 32596036, 2020).
intestinal neuroendocrine tumors (1 paper, 2023). "These events are not observed in intestinal neuroendocrine tumors and, accordingly, the organoid culture showed prominent nuclear expression of both ATRX and DAXX." (PMID 37082125, 2023).
ischemia (1 paper, 2023). A hypoperfusion of the BLOOD through an organ or tissue caused by a PATHOLOGIC CONSTRICTION or obstruction of its BLOOD VESSELS, or an absence of BLOOD CIRCULATION. "Partial ATP depletion causes the fast activation of DAXX, Fas, and JNK phosphorylation and apoptosis in animals with ischemia‐induced acute kidney damage." (PMID 37553782, 2023).
kidney cancer (1 paper, 2021). Primary or metastatic malignant neoplasm involving the kidney. "Interestingly, DAXX has also been associated with degradation of Gli2 and PTEN in kidney cancer." (PMID 34680332, 2021).
myocardial ischemia (1 paper, 2024). A disorder of cardiac function caused by insufficient blood flow to the muscle tissue of the heart. "Furthermore, death-domain associated protein 6 (DAXX) regulates Fas protein-dependent apoptotic signaling during myocardial ischemia–reperfusion injury." (PMID 39639374, 2024).
osteoporosis (1 paper, 2015). A condition of reduced bone mass, with decreased cortical thickness and a decrease in the number and size of the trabeculae of cancellous bone (but normal chemical composition), resulting in increased fracture incidence. "Above all, our findings suggested a novel mechanism for osteoporosis, which is attenuation of monocyte apoptosis, as supported by the 4 apoptosis genes’ (DAXX, PLK3, VDAC1 and PDCD5) down-regulation in the low BMD subjects." (PMID 25659073, 2015).
peritoneal effusions (1 paper, 2020). "In the present study, significantly higher DAXX expression was found in pleural compared to peritoneal effusions and in post-chemotherapy compared to pre-chemotherapy effusions, findings that suggest an association between this protein and disease progression in HGSC." (PMID 32533344, 2020).
progeria (1 paper, 2022). "Notably, the DAXX gene itself was found to be over-expressed exclusively in sample GOE615, underlying the link from genetic variation to this specific progeria sample phenotype." (PMID 35260714, 2022).
prostate (1 paper, 2025). "The precise roles of ATRX and DAXX in human prostate carcinogenesis remain incompletely understood, and further research is needed to clarify their potential clinical relevance." (PMID 41472189, 2025).
renal fibrosis (1 paper, 2021). A final common manifestation of a wide variety of chronic kidney diseases characterized by glomerulosclerosis and tubulointerstitial fibrosis. "Indeed, as a therapeutic approach to reversing fibrosis, interference with SMAD2 acetylation either by the DAXX transcription factor, as shown in hepatocytes, or by the p300/CBP inhibitor garcinol, as shown in a nondiabetic renal fibrosis model, can be considered." (PMID 34576109, 2021).
staphylococcus aureus infection (1 paper, 2020). An infectious process in which the bacteria Staphylococcus aureus is present. "We identified the protein association network of Staphylococcus aureus infection genes and ALT-related genes and found that DAXX and FAS were functionally connected." (PMID 32784588, 2020).
thymic carcinoma (1 paper, 2022). Thymic carcinoma (TC) is a type of thymic epithelial neoplasm characterized by a high malignant potential. "In this context, the lymphocyte poor TETs, namely thymomas B3 and thymic carcinomas, showed a decreased expression of DAXX, which was predominant in the rest type of TETs, possibly having a role in the evolution of these tumors." (PMID 35955489, 2022).
thyroid cancer (1 paper, 2019). "Conversely, ALT mechanisms as determined by mutations in ATRX and DAXX, are not reported in non-medullary cells derived thyroid cancers in many different studies, thus an involvement of these mechanisms in telomere deregulation may be likely excluded in this pathogenic environment." (PMID 31200515, 2019).
tuberous sclerosis (1 paper, 2023). Hereditary disease characterized by seizures, intellectual disability, developmental delay, and skin and ocular lesions. "We set up a model able to represent frequently reported PanNETs drivers in patient cohorts, such as Menin-1 (MEN1), Death domain associated protein (DAXX), Tuberous Sclerosis (TSC), as well as wild-type tumors." (PMID 37270586, 2023).
urothelial bladder carcinomas (1 paper, 2025). "In contrast, urothelial carcinomas of the bladder displayed reduced expression of DAXX and ATRX in tumours with increased aggressiveness." (PMID 41472189, 2025). "A loss of expression for DAXX and ATRX in human medicine is associated with a worse prognosis in PanNENs and urothelial bladder carcinomas." (PMID 41472189, 2025).